SMAD9 (SMAD family member 9)
Description:
Transcriptional modulator activated by BMP (bone morphogenetic proteins) type 1 receptor kinase. SMAD9 is a receptor-regulated SMAD (R-SMAD).
Synonyms: MADH6; MADH9; SMAD8; SMAD8/9; PPH2; SMAD8A; SMAD8B
Tractability: PROTAC: ubiquitination databases record sites on it.
Gene: Protein-coding gene on chromosome 13 (36,844,831 to 36,920,887, reverse strand). Ensembl gene ENSG00000120693.
Subcellular location: Cytoplasm; Nucleus
Subcellular location (Human Protein Atlas): Nucleoplasm; Cytosol
Pathways (Reactome):
Signal Transduction: Signaling by BMP
Gene Ontology:
Molecular function: protein binding; DNA-binding transcription factor activity; DNA-binding transcription factor activity, RNA polymerase II-specific; I-SMAD binding; RNA polymerase II cis-regulatory region sequence-specific DNA binding
Biological process: BMP signaling pathway; intracellular iron ion homeostasis; osteoblast differentiation; anatomical structure morphogenesis; cell differentiation; cellular response to BMP stimulus; positive regulation of transcription by RNA polymerase II; regulation of transcription by RNA polymerase II; SMAD protein signal transduction; stem cell differentiation; transforming growth factor beta receptor signaling pathway; cellular response to growth factor stimulus; developmental process; regulation of DNA-templated transcription; transforming growth factor beta receptor superfamily signaling pathway
Cellular component: cytosol; nucleoplasm; chromatin; cytoplasm; heteromeric SMAD protein complex; nucleus; SMAD protein complex; transcription regulator complex
Genetic constraint (gnomAD): Loss-of-function variants: 34 observed, 44.47 expected, observed/expected ratio (o/e) 0.76, 90% interval 0.58 to 1.02. The upper end of that interval is the gene's LOEUF score, 1.02, which puts it in group 4 of 6, group 1 being the genes least tolerant of losing a copy. Missense variants: 532 observed, 587.48 expected, observed/expected ratio (o/e) 0.91, 90% interval 0.84 to 0.97. Synonymous variants: 226 observed, 233.02 expected, observed/expected ratio (o/e) 0.97, 90% interval 0.87 to 1.08.
Gene-disease validity (ClinGen):
ClinGen rates the evidence that SMAD9 causes each of these diseases.
pulmonary arterial hypertension (autosomal dominant): Definitive. Pulmonary arterial hypertension (PAH) is a group of diseases characterized by mean pulmonary artery pressure >20 mmHg and elevated pulmonary arterial resistance leading to right heart failure.
Homologues: Orthologues: chimpanzee SMAD9 (99% identical), macaque SMAD9 (99% identical), dog SMAD9 (96% identical), pig SMAD9 (94% identical), rabbit SMAD9 (78% identical), Drosophila melanogaster Mad (71% identical), Caenorhabditis elegans sma-2 (50% identical). Paralogues in human: SMAD1 (80% identical), SMAD5 (78% identical), SMAD2 (60% identical), SMAD3 (60% identical), SMAD4 (41% identical), SMAD6 (28% identical), SMAD7 (24% identical).
Diseases named in the same sentence as SMAD9 in open-access papers:
SMAD9 is named in the same sentence as 63 diseases in open-access papers, as found by Europe PMC text mining. Sharing a sentence is not in itself a finding about the gene and the disease. The quoted sentences say what the papers report.
pulmonary arterial hypertension (9 papers, 2015 to 2025). "Rare variants such as SMAD1, SMAD4, and SMAD9 associated with genetics with pulmonary arterial hypertension are also located in the cytoplasm and nucleus." (PMID 40710838, 2025). "Rare sequence variants in SMAD9 were reported to contribute to pathogenesis of pulmonary arterial hypertension." (PMID 38033031, 2023). "SMAD9 protein is associated with colorectal neoplasms, familial pulmonary hypertension and pulmonary arterial hypertension." (PMID 38033031, 2023). "According to the pulmonary hypertension gene curation expert panel of pulmonary hypertension of ClinGen, the association of BMPR2, KCNK3, KDR, SMAD9, and TBX4 and PH is definitive, GDF2 is strong, and AQP1 has a limited disease relationship." (PMID 35627312, 2022). "ALK1 might also phosphorylate SMAD9 (formerly known as SMAD8) and mutations in Smad9 are associated with defective pulmonary vascular remodelling in mice and are a rare cause of pulmonary arterial hypertension in humans." (PMID 36250069, 2022). "Previous studies have shown that TGF-β pathway plays an important role in PAH by regulating pulmonary vascular remodeling, variation of several TGF-β family receptor members, such as ACVRL1, ENG and SMAD9, are pathogenic genes of hereditary pulmonary arterial hypertension patients." (PMID 34310344, 2021).
lung carcinoma (8 papers, 2020 to 2025). "In summary, poor survival is associated with PPARGC1B, EIF4E3, and SMAD9 low gene expression in breast, colon and lung cancer." (PMID 39940786, 2025). "SMAD9 overexpression is associated with the prevalence of hamartomatous polyposis and is a prognostic factor for lung cancer." (PMID 34485158, 2021). "Moreover, the downregulations of PPARGC1B, EIF4E3, and SMAD9 are associated with poor survival in breast, colon, and lung cancer patients." (PMID 39940786, 2025). "Studies related to lung cancer have found that the expressions of SMAD6, SMAD7, and SMAD9 in SMADs are downregulated in lung cancer and significantly correlated with the prognosis of patients." (PMID 36969909, 2023). "SMAD9:rs7333607 is located in the intron region of the SMAD9 gene and only correlated with lung cancer survival." (PMID 34307117, 2021). "Interestingly, most of the downregulated genes, including PPARGC1B, EIF4E3, and SMAD9, were classified with poor survival in breast, colon and lung cancer." (PMID 39940786, 2025). "Methylation, phosphorylation, and dephosphorylation of SMAD9 may function in the progression of lung cancer." (PMID 36245988, 2022). "It was found that SMAD9 may be regulated by methylation, phosphorylation and dephosphorylation in the occurrence and development of lung cancer." (PMID 33648465, 2021). "This study highlights the significant contribution of PPARGC1B, EIF4E3, and SMAD9 out of 11 RBP genes as prognostic predictors in patients with breast, colon, and lung cancers and their potential application in personalized therapy." (PMID 39940786, 2025). "FERMT2 together with FKBP3, SMAD9, GATA2, and ITIH4 was constructed as a prognostic signature of lung cancer based on the differential expression of immune genes." (PMID 36253873, 2022). "Meanwhile, there is plenty of evidence that SMAD9, ITIH4 and GATA2 have close connection with the initiation, progression and prognosis of various malignancies including lung cancer." (PMID 33648465, 2021).
lung adenocarcinoma (5 papers, 2020 to 2023). A carcinoma that arises from the lung and is characterized by the presence of malignant glandular epithelial cells. "Nomogram analysis was also used in this study, and the results also showed that SMAD9, KHDRBS2, and RBM10 had a certain risk correlation with the survival rate of lung adenocarcinoma patients." (PMID 37509501, 2023). "In addition, a low expression of SMAD9 is related to a poor OS in lung adenocarcinoma." (PMID 36118697, 2022). "In order to verify the clinical value of the model, we finally examined the expression of FERMT2, FKBP3, SMAD9, GATA2 and ITIH4 in 30 lung adenocarcinoma tissues by immunohistochemistry, considering the availability of antibodies." (PMID 33648465, 2021).
Hypertension (4 papers, 2016 to 2025). The presence of chronic increased pressure in the systemic arterial system. "Common gene mutation sites were analyzed to investigate the the association between single nucleotide polymorphisms (SNPs) of the BMPR2, ACVRL1, and SMAD9 genes with hypertension risk." (PMID 30617053, 2019). "Two DEGs (Irf8 and Smad9) are associated with hypertension and encode TFs (both are downregulated)." (PMID 38928385, 2024). "Many reports showed that CETP, LIPC and LIPG were associated with HDL and LDL and that MTHRR had known main effects for LDL and blood pressure, NR1I3 for lipid metabolism, PLTP for LDL, FOXO1 for LDL and hypertension, SMAD9 for hypertension, and CSMD1 for SBP." (PMID 27104857, 2016).
breast carcinoma (3 papers, 2019 to 2025). "Genetic changes in the SMAD9 gene were observed in 2.1% of patients with breast cancer." (PMID 38514720, 2024).
dementia (3 papers, 2022 to 2023). Loss of intellectual abilities interfering with an individual's social and occupational functions. "Upregulation of SMAD9 was associated with dementia, while downregulation of POLR2F was associated with aging-related hypoxic stress." (PMID 36118697, 2022). "In this RBPS, SMAD9 was found to be associated with dementia; POLR2F and ERI1 were identified to be associated with aging." (PMID 36118697, 2022). "Surprisingly, the study discovered a relationship between SMAD9 overexpression and dementia, indicating a possible link between SMAD9 and cognitive abnormalities." (PMID 37884559, 2023). "A study reported that stroke was associated with cognitive impairment and dementia in older adults, and the six RNA-binding protein (RBP) genes (POLR2F, DYNC1H1, SMAD9, TRIM21, BRCA1, and ERI1) might participate in the process by mediating the hypoxic responses and angiogenesis." (PMID 37006557, 2023).
endometrial cancer (3 papers, 2021 to 2023). Primary or metastatic malignant neoplasm involving the endometrium (mucous membrane that lines the endometrial cavity). "Our data support previous findings suggesting that SMAD9 may inhibit transcriptional activity in endometrial cancer." (PMID 34925436, 2021). "Additionally, the four genes (FN1, DUSP4, LEF1, and SMAD9) identified can shed light on the mechanisms of recurrence in endometrial cancer." (PMID 34485158, 2021). "employed transcriptome sequencing technology to analyze 5 pairs of endometrial cancer tissues and normal endometrial tissues, revealing downregulation of ID1, IGF1, GDF7, SMAD9, TGF-β, and WNT4 expression alongside upregulation of GDF5, INHBA, and ERBB4 in endometrial cancer." (PMID 38239355, 2023).
gastric cancer (3 papers, 2020 to 2022). A primary or metastatic malignant neoplasm involving the stomach. "The high expression level of SMAD9 was associated with poor OS in all gastric cancer, gastrointestinal cancer, diffuse gastric cancer and mixed gastric cancer." (PMID 34138687, 2021). "Although the link of high expression to better OS makes SMAD9 upregulation an unlikely driver of acidosis-induced pro-tumorigenic effects, activating SMAD9 mutations were linked to some gastric cancers." (PMID 32764426, 2020). "Analysis showed that high expression levels of SMAD1, SMAD2, and SMAD4 are associated with a better survival rate of gastric cancer patients, whereas SMAD3, SMAD5, SMAD6, SMAD7 and SMAD9 are associated with poor prognosis." (PMID 34138687, 2021). "Therefore, overexpression of SMAD9 is correlated with a poor survival rate in gastric cancer patients." (PMID 34138687, 2021). "Finally, we verified that TGFB1I1, TGFBR1, SMAD9 and SMAD4 are low expressed in gastric cancer by immunohistochemistry at the protein level, and RCAN2 is also low expressed in gastric cancer." (PMID 36483555, 2022).
glioma (3 papers, 2022 to 2025). A benign or malignant brain and spinal cord tumor that arises from glial cells (astrocytes, oligodendrocytes, ependymal cells). "Stratification of gliomas according to the latest WHO 2021 classification revealed elevated SMAD9 mRNA levels in IDH-wildtype glioblastoma compared to both IDH-mutant astrocytomas and oligodendrogliomas." (PMID 41331572, 2025). "Among them, POLR2F, DYNC1H1, and SMAD9 in tumor tissues of patients with glioma were downregulated as compared to normal tissues adjacent to cancer, while TRIM21, BRCA1, and ERI1 were upregulated." (PMID 36118697, 2022). "Lin established a 6-RBP gene signature consisting of POLR2F, DYNC1H1, SMAD9, TRIM21, BRCA1, and ERI1 in another bioinformatics work, allowing for a complete assessment of glioma and ischemic stroke." (PMID 37884559, 2023). "First, six prognostic-related RBP genes (POLR2F, DYNC1H1, SMAD9, TRIM21, BRCA1, and ERI1) were obtained from the TCGA-glioma dataset." (PMID 36118697, 2022). "The volcanic plot showed the differential analysis results of these six RBP genes, which showed that POLR2F and DYNC1H1 were downregulated in glioma, while TRIM21, BRCA1, ERI1, and SMAD9 were upregulated in glioma." (PMID 36118697, 2022). "In all WHO grade II-IV gliomas, DNAss was positively correlated with the RBPS score, ERI1, BRCA1, and TRIM21, while negatively correlated with POLR2F, DYNC1H1, and SMAD9 [Spearman correlation, Benjamini-Hochberg (BH)-adjusted p < 0.05]." (PMID 36118697, 2022).
neuroblastoma (3 papers, 2022 to 2025). Neuroblastoma (NB) is the most common solid, extracranial childhood tumor. "SMAD9 is an independent prognostic factor for high-risk neuroblastoma, and its expression is directly regulated by MYCN through SEs." (PMID 41244073, 2025). "Indeed, the ATRA IC50s were almost perfectly correlated with SMAD9 expression levels in both the GDSC (R = −0.92, P = 4.2 × 10−6) and DepMap (R = −0.81, P = 4.8 × 10−4), with SMAD9 expression also prognostic in neuroblastoma patients." (PMID 40021625, 2025). "SMAD9 is a regulatory SMAD and transcription factor that acts as one of the main downstream effectors of BMP signaling, which is highly expressed in neuroblastoma." (PMID 40021625, 2025). "SMAD9 forms a positive transcriptional feedback loop with MYCN and represents a unique tumor dependency for MYCN-amplified neuroblastoma." (PMID 36539767, 2022). "This study delineates that SMAD9 forms a positive transcriptional feedback loop with MYCN and represents a unique tumor-dependency for MYCN-amplified neuroblastoma." (PMID 36539767, 2022).
chondrodysplasia (2 papers, 2021 to 2026). "Furthermore, the downstream mediators of BMP signaling, namely SMAD1, SMAD5, and SMAD8 (also known as SMAD9) are essential for bone formation, as their deficiency in mice leads to lethal chondrodysplasia." (PMID 33673480, 2021).
colon cancer (2 papers, 2020 to 2025). "SMAD9, a receptor-SMAD activated by Bone Morphogenetic Protein (BMP) receptors, was also upregulated by acidosis in colon cancer cells." (PMID 32764426, 2020).
heritable pulmonary arterial hypertension (2 papers, 2019 to 2021). Heritable pulmonary arterial hypertension (HPAH) is a form of pulmonary arterial hypertension (PAH), occurring due to mutations in PAH predisposing genes or in a familial context. "If SMAD9 have heterozygous mutations, it will cause heritable pulmonary arterial hypertension (HPAH), a serious lung vascular disease." (PMID 31888623, 2019).
melanoma (2 papers, 2017 to 2021). A malignant, usually aggressive tumor composed of atypical, neoplastic melanocytes. "In any case, upregulation of SMAD9 due to BMP4 treatment has also been recently reported in various cell types, for example in primary fibroblasts, hepatocellular carcinoma and melanoma cells." (PMID 28077088, 2017).
osteoporosis (2 papers, 2020). A condition of reduced bone mass, with decreased cortical thickness and a decrease in the number and size of the trabeculae of cancellous bone (but normal chemical composition), resulting in increased fracture incidence. "Lowering SMAD9 as a potential novel anabolic mechanism for osteoporosis therapeutics warrants further investigation." (PMID 31525280, 2020). "Given the benign phenotype observed in c.65T>C, p.Leu22Pro SMAD9 carriers, our findings suggest that SMAD9 is worth consideration as a drug target for osteoporosis." (PMID 31525280, 2020). "Our findings support SMAD9, and its role within the SMAD9‐dependent BMP signaling pathway, as a potential novel anabolic target for osteoporosis therapeutics that warrants further investigation." (PMID 31525280, 2020). "Our findings support SMAD9 as a novel HBM gene and a potential novel osteoanabolic target for osteoporosis therapeutics." (PMID 31525280, 2020). "A study on zebrafish helped to unravel the role of Smad9 as a downstream inhibitor of the BMP signaling pathway and reducer of osteoblast activity, providing evidence that Smad9 can be used as anabolic target for the treatment of osteoporosis." (PMID 32824602, 2020).
pulmonary hypertension (2 papers, 2016 to 2022). Increased pressure within the pulmonary circulation due to lung or heart disorder. "In this study, we analyzed 7 PAH-causing genes including BMPR2, ACVRL1, ENG, SMAD9, CAV1, KCNK3, and CBLN2 in 49 CTEPH patients and 17 patients recovered from pulmonary embolism (PE) but without pulmonary hypertension(PH)." (PMID 26820968, 2016).
adenoma (1 paper, 2025). A neoplasm arising from the epithelium. "Conversely, SMAD9 showed a significant upregulation in adenoma, while CIRBP was downregulated only in tumors." (PMID 39980011, 2025).
Alzheimer disease (1 paper, 2022). A progressive, neurodegenerative disease characterized by loss of function and death of nerve cells in several areas of the brain leading to loss of cognitive function such as memory and language. "Further analyses revealed that SMAD9 in the RBPS was associated with the Alzheimer's disease onset." (PMID 36118697, 2022).
diabetes (1 paper, 2022). "A recent study revealed that SMAD9 was highly expressed in the blood of diabetes patients and in streptozotocin-induced rat retinas, which indicated that SMAD9 was closely related with diabetic retinopathy." (PMID 36213291, 2022).
follicular adenoma (1 paper, 2021). "A previous study showed that SMAD9 was significantly downregulated in the normal thyroid compared to the follicular variant of papillary thyroid carcinoma and follicular adenoma." (PMID 34925436, 2021).
meningioma (1 paper, 2007). A generally slow growing tumor attached to the dura mater. "In line with the microarray data, the PCR data showed a decrease in the median expression level of BMP4, SMAD9, JUN, RUNX2 and an increase in the median expression level of FKBP1A in Grade 3 meningiomas when compared to Grade 1 meningiomas." (PMID 17937814, 2007).
osteoarthritis (1 paper, 2020). A noninflammatory degenerative joint disease occurring chiefly in older persons, characterized by degeneration of the articular cartilage, hypertrophy of bone at the margins and changes in the synovial membrane. "ADAMTS5, NOTCH1, SMAD9, and SOX9 genes, enriched in the osteoarthritis pathway, were predicted as targets of a novel miRNA (3_17250)." (PMID 32316683, 2020).
sclerosteosis (1 paper, 2020). "The clinical phenotype of c.65T>C, p.Leu22Pro SMAD9 HBM has many features in common with that of LRP5 HBM but lacks the deleterious features that characterize SOST HBM (sclerosteosis)." (PMID 31525280, 2020).
Type 1 Diabetes (1 paper, 2024). "Additionally, the DCT gene has been linked with the gut microbiota through the melatonin pathway, and the expression of SMAD9 has been linked to Bacteroides dorei in the context of Type 1 Diabetes." (PMID 38892420, 2024).